EID3 (EP300 interacting inhibitor of differentiation 3)
Description:
Tissue-specific component of the SMC5-SMC6 complex, a complex involved in repair of DNA double-strand breaks by homologous recombination. The complex may promote sister chromatid homologous recombination by recruiting the SMC1-SMC3 cohesin complex to double-strand breaks. The complex is required for telomere maintenance via recombination and mediates sumoylation of shelterin complex (telosome) components. Acts as a repressor of nuclear receptor-dependent transcription possibly by interfering with CREBBP-dependent coactivation. May function as a coinhibitor of other CREBBP/EP300-dependent transcription factors.
Synonyms: NS4EB; FLJ25832; NSMCE4B; NSE4B
Tractability: PROTAC: ubiquitination databases record sites on it.
Gene: Protein-coding gene on chromosome 12 (104,303,739 to 104,305,205, forward strand). Ensembl gene ENSG00000255150.
Subcellular location: Nucleus; Cytoplasm; Chromosome, telomere
Subcellular location (Human Protein Atlas): Nucleoli; Nucleoplasm
Pathways (Reactome):
Metabolism of proteins: SUMOylation of DNA damage response and repair proteins
Gene Ontology:
Molecular function: protein binding
Biological process: chromatin looping; DNA repair; double-strand break repair via homologous recombination; protein sumoylation; regulation of telomere maintenance
Cellular component: cytoplasm; nucleolus; nucleoplasm; nucleus; Smc5-Smc6 complex; chromosome, telomeric region; chromosome
Genetic constraint (gnomAD): Loss-of-function variants: 5 observed, 3.81 expected, observed/expected ratio (o/e) 1.31, 90% interval 0.64 to 1.91. That is too few expected variants to judge how well the gene tolerates losing a copy. Missense variants: 466 observed, 433.36 expected, observed/expected ratio (o/e) 1.08, 90% interval 1 to 1.16. Synonymous variants: 164 observed, 157.02 expected, observed/expected ratio (o/e) 1.04, 90% interval 0.92 to 1.19.
Homologues: Orthologues: rat Eid3 (73% identical), mouse Eid3 (70% identical), zebrafish nsmce4a (41% identical), Caenorhabditis elegans nse-4 (21% identical), Drosophila melanogaster Nse4 (17% identical). Paralogues in human: NSMCE4A (50% identical).
Diseases named in the same sentence as EID3 in open-access papers:
EID3 is named in the same sentence as 13 diseases in open-access papers, as found by Europe PMC text mining. Sharing a sentence is not in itself a finding about the gene and the disease. The quoted sentences say what the papers report.
colorectal cancer (3 papers, 2017 to 2024). A primary or metastatic malignant neoplasm that affects the colon or rectum. "Elevated expression of EID3 serves as an adverse prognostic indicator for patients with colorectal cancer." (PMID 38544827, 2024). "In fact, it has been reported that EID3 is involved in cell differentiation inhibition and cancer stem cell formation in colorectal cancer." (PMID 29290942, 2017). "High expression of EID3 is an adverse prognostic indicator for patients with colorectal cancer." (PMID 35186021, 2022).
gastric cancer (2 papers, 2022 to 2023). A primary or metastatic malignant neoplasm involving the stomach. "Recently, Lu and Zhang reported that radiochemotherapy triggers DNA damage response in gastric cancer cells reprogramming them into gastric cancer stem-like cells via the EID3-NAMPT-Wnt/β-catenin axis." (PMID 37686684, 2023). "The results showed that the higher the tumor histological grades and pathological stages of gastric cancer patients were, the higher the EID3 expression level was." (PMID 36153608, 2022). "Our study indicates that gastric cancer cells can be endowed with stemness traits via EID3-NAMPT-Wnt/β-catenin axis in response to radiochemotherapy." (PMID 36153608, 2022). "Our correlation analysis also revealed that EID3 was positively correlated with the Wnt pathway in gastric cancers, presenting a new role of EDI3 in the Wnt pathway." (PMID 36153608, 2022). "Kaplan–Meier survival analysis revealed that the high level of EID3 was remarkably correlated with poor overall survival of gastric cancer patients." (PMID 36153608, 2022). "In this mechanism, radiochemotherapy triggers DNA damage response accompanied by elevated levels of EID3, a typical DNA repair gene, which interacts with NAMPT to promote stemness via upregulating Wnt signaling pathway, manifested by enhanced tumorsphere/tumor formation in gastric cancer." (PMID 36153608, 2022). "Taken together, these findings revealed that the radiotherapy or chemotherapy promoted the expression of DNA repair genes (APLF, EID3, EME2, NPAS2 and POLN) of gastric cancer non-stem stem cells to trigger DNA repair, resulting in the biogenesis of GCSCs." (PMID 36153608, 2022).
Cirrhosis (1 paper, 2025). A chronic disorder of the liver in which liver tissue becomes scarred and is partially replaced by regenerative nodules and fibrotic tissue resulting in loss of liver function. "Notably, EID3, MIR150, and ZNF154 have been reported to exhibit differential expression between cirrhosis patients and HCC patients, suggesting their potential as biomarkers for early-stage HCC." (PMID 40500793, 2025).
colon cancer (1 paper, 2022). "In fact, it has been reported that colon cancer cells with high expression of EID3 are more resistant to radiotherapy and chemotherapy and promote the formation of tumor stem cells." (PMID 36071872, 2022). "It has been reported that colon cancer cells with high expression of EID3 participate in the inhibition of differentiation of colon cancer cells and the formation of tumor stem cells." (PMID 36071872, 2022).
glioma (1 paper, 2023). A benign or malignant brain and spinal cord tumor that arises from glial cells (astrocytes, oligodendrocytes, ependymal cells). "Interestingly, high expression of EID3 in glioma is associated with poorer prognosis." (PMID 37086071, 2023). "Among these, EID3, MGMT, PMS1, and NUDT1 were significantly related to the prognosis and survival of glioma patients, and the high-risk score group had a significantly shorter survival time." (PMID 37086071, 2023). "EID3 showed a trend of low expression in the brain tissue of glioma patients." (PMID 37086071, 2023).
hepatoma (1 paper, 2011). "NSE4b/EID3 was first identified as a member of the EID (E1A-like inhibitor of differentiation) family of transcriptional repressors and was shown to inhibit transcriptional activation from several promoters in HuH7 human hepatoma cells." (PMID 21364888, 2011).
osteosarcoma (1 paper, 2022). A usually aggressive malignant bone-forming mesenchymal neoplasm, predominantly affecting adolescents and young adults. "We examined EID3 expression in three human osteosarcoma cell lines and found that EID3 protein was overexpressed in all three osteosarcoma cell lines compared to primary human osteoblasts cell line hFOB." (PMID 36071872, 2022). "In this study, we investigated the expression and biological function of EID3 in osteosarcoma cells." (PMID 36071872, 2022). "Overexpression of EID3 in osteosarcoma cells generated more spherical clones, enhanced the expression of stemness-associated genes, and promoted chemoresistance, invasion, and metastasis." (PMID 36071872, 2022). "Next, we used transcriptome sequencing to explore the mechanism by which EID3 regulates the stemness of osteosarcoma cells." (PMID 36071872, 2022). "Further in vivo studies based on animal models are needed to confirm the role of EID3 in the maintenance of the stemness of osteosarcoma cells." (PMID 36071872, 2022). "Taken together, these findings indicate that PI3K-Akt signaling pathway contributes to EID3-induced osteosarcoma cancer stemness." (PMID 36071872, 2022). "RNA sequencing and bioinformatics analysis revealed that PI3K-Akt signaling pathway and MAPK pathway­related genes were enriched in osteosarcoma cells with high expression of EID3." (PMID 36071872, 2022). "The aim of this study is to elucidate molecular mechanism by which E1A-like inhibitor of differentiation 3 (EID3) promotes cancer stem cell-like phenotypes in osteosarcoma." (PMID 36071872, 2022). "We demonstrated that the mRNA and protein levels of EID3 significantly increased in osteosarcoma cells." (PMID 36071872, 2022). "We found that osteosarcoma cells overexpressing EID3 generated more osteospheres and promoted cell invasion and had high expression of Sox2 and the stem cell marker CD133." (PMID 36071872, 2022). "In conclusion, our study demonstrates high expression of EID3 in osteosarcoma cells, especially in sphere-cultured osteosarcoma cells." (PMID 36071872, 2022). "To explore the role of EID3 in osteosarcoma, we overexpressed or deleted the expression of EID3 in osteosarcoma cells and proved that EID3 played an important role in maintaining the stemness of osteosarcoma cells based on sphere-forming assay, chemoresistance, and cell migration and invasion assay." (PMID 36071872, 2022). "Whether EID3 maintains the stemness of osteosarcoma cells by upregulating the expression of GRB2 and activating PI3K-AKT pathway remains to be further explored." (PMID 36071872, 2022). "Furthermore, osteosarcoma cells overexpressing EID3 had increased ability to grow in suspension as osteospheres with high expression of Sox2 and stem cell marker CD133." (PMID 36071872, 2022). "In addition, EID3 expression was higher in bone mesenchymal stem cells (BMSCs) than in other osteosarcoma cells." (PMID 36071872, 2022). "In addition, knockdown of EID3 reduced sphere formation and inhibited osteosarcoma cell migration and invasion." (PMID 36071872, 2022). "To determine whether EID3 can enhances stemness of osteosarcoma cells, we generated EID3-overexpressing MG-63 cell line (MG-63-EID3) and control cell line (MG-63-Vector)." (PMID 36071872, 2022). "Furthermore, the stem cells in osteosarcoma cells were enriched by sphere culture, and the expression of EID3 was increased in these osteosphere cells." (PMID 36071872, 2022). "Our results showed that EID3 was highly expressed in MG-63, U2OS, and HOS osteosarcoma cell lines, especially in MG-63 cells." (PMID 36071872, 2022). "EID3 overexpression not only improved stem cell phenotype but also enhanced the enrichment of CD133+ cells and the expression of stem cell-related markers OCT3/4, ABCG2, and NANOG in osteosarcoma cells." (PMID 36071872, 2022). "However, the role of EID3 in osteosarcoma has not been reported." (PMID 36071872, 2022).
cancer (7 papers, 2014 to 2025). A tumor composed of atypical neoplastic, often pleomorphic cells that invade other tissues. "EID3, belonging to a member of the IED family, is involved in regulating tumor development in different cancer types." (PMID 37086071, 2023).
tumor (6 papers, 2017 to 2025). "The results indicated that the tumor growth in the mice injected with the EID3-silenced GCSCs was significantly repressed compared with that in the control mice, while the tumor growth in the mice treated with EID3 rescue was comparable to that of the control." (PMID 36153608, 2022). "Five tumor antigens were identified, of which antibody levels against the EID3 antigen was significantly higher in the patient group." (PMID 29290942, 2017). "We examined the accuracy of serum anti-EID3 Ab levels and serum CgA levels to serve as a tumor marker for NF-pNETs." (PMID 29290942, 2017). "Differences in the mRNA expression of EID3 in tumor and normal pancreatic tissues were analyzed by quantitative real time RT-PCR (qPCR) for six NF-pNET patients in which both tumor and normal pancreatic tissue were preserved." (PMID 29290942, 2017). "The expression and distribution of EID3 proteins in tumor and normal pancreatic tissue was examined by immunohistochemical staining using 31 resected tissue samples from NF-pNET patients." (PMID 29290942, 2017). "Blocking this axis (i.e., targeting EID3) along with radiochemotherapy might represent a potential strategy to sensitize CSCs to radiochemotherapy and further reinforce the anti-tumor effects of conventional treatments." (PMID 36153608, 2022). "In conclusion, serum anti-EID3 antibody levels may be useful as a tumor marker for prediction of tumor recurrence in NF-pNETs." (PMID 29290942, 2017). "In addition, the AUC value calculated by ROC analysis indicated that serum anti-EID3 Abs may be a tumor marker with moderate accuracy." (PMID 29290942, 2017). "In conclusion, we identified five NF-pNET tumor antigens by the SEREX technology, of which the antibody levels against EID3 antigen were significantly higher in NF-pNET patients than in the HDs." (PMID 29290942, 2017). "There was no heterogeneity in the protein expression of EID3 in the tumor tissue." (PMID 29290942, 2017).
infection (2 papers, 2022). The state of being infected such as from the introduction of a foreign agent such as serum, vaccine, antigenic substance or organism. "Accelerated DENV2 replication damaged host DNA as mutant infection was dependent on host DNA damage repair factors, namely RAD21, EID3 and NEK5." (PMID 36514984, 2022). "As expected, D2C replication was significantly reduced in EID3 and NEK5 knockout cells compared to the parental Huh7.5.1 cells at both post-infection timepoints tested." (PMID 36514984, 2022).
EID3 also shares sentences with these, for which no sentence is quoted: autoimmune disease (1 paper); leukoplakia (1); pancreatic neuroendocrine tumor (1).